TLR4 (toll like receptor 4)
Diseases named in the same sentence as TLR4 in open-access papers (continued):
Sharing a sentence is not in itself a finding about the gene and the disease.
hyperlipidemia (continued). "Therefore, blockade of excessive TLR4 expression is an available therapeutic management for MI/R superimposed on hyperlipidemia." (PMID 27731393, 2016). "Moreover, when the participants had hyperlipidemia, the OR (95% CI) was 3.269 (1.398–7.644) between TLR4 rs11536889 and MyD88 rs7744 (p value for interaction = 0.006)." (PMID 26959040, 2016). "And TLR4 was up-regulated significantly in response to MI/R+hyperlipidemia than MI/R (P < 0.01)." (PMID 27731393, 2016). "Since endotoxin (produced by gut microflora) is a ligand for TLR4, we further hypothesize that vascular defects due to lipidemia might require TLR4." (PMID 24219792, 2013). "Notably, hyperlipidemia stimulation significantly decreased the mRNA expression levels of TLR-4 and TLR-2 by 69.1% (P < 0.001) and 68.1% (P < 0.05), and 52.1% (P < 0.01) and 38.6% (P < 0.05), respectively, in PCSK9liver(−/−) and PCSK9liver(+/−) mice as compared to that of PCSK9liver(+/+) mice." (PMID 39963241, 2025). "Hence, in the current study, we investigated whether HSYA mitigated MI/R superimposed on hyperlipidemia injury and the role of TLR4 in this process." (PMID 27731393, 2016). "Because such attenuation is not seen in wild-type mice, in which the expression of Tlr2 and Tlr4 was further elevated after long-term infection compared with short-term infection, the deletion of the ApoE gene and/or the resulting hyperlipidemia may have affected the endothelial response." (PMID 21625524, 2011). "Controlled the body weight, blood glucose and related organ indices, counteracted hyperlipidemia and IR triggered; regulated AST and ALT; down-regulated TLR4/NF-κB signaling." (PMID 36671814, 2023). "Inhibited fat accumulation and body weight, hyperlipidemia; reduced LPS level; decreased levels of TNF-α and IL-1β; increased acetate and butyrate production; inhibited LPS/TLR4/NF-κB signaling pathway." (PMID 36671814, 2023). "Periodontal tissues in ApoE−/− hyperlipidemia model rats are reported to exhibit more TRAP-positive multinuclear cells and increased TLR2 and TLR4 expression levels, suggesting that high oxLDL concentration effects osteoclastogenesis via the elevation of TLRs." (PMID 29859535, 2018). "TLR4 levels of HSYA (16 mg/kg and 32 mg/kg) groups were significantly lower than MI/R+hyperlipidemia group (P < 0.01)." (PMID 27731393, 2016). "We also shed light on the understanding of how hyperlipidemia and saturated fatty acids can activate the EGFR signaling pathway through TLR4 and c-Src/EGFR complex." (PMID 27014908, 2016). "High-fat diet induced hyperlipidemia worsened MI/R mediated heart injury (elevation of infarct size, CK-MB and LDH activity), activated TLR4 over-expression in hearts, released inflammatory cytokines (LPS, TNF-α and IL-1β) excessively." (PMID 27731393, 2016). "Mechanistically, hyperlipidemia induced by HFD feeding acts as the first stimulation for TI via lysoPC stimulation, oxidized low-density lipoprotein (oxLDL) binding to CD36, TLR4 /TLR2 and nucleotide-binding domain, leucine-rich-containing family, pyrin domain-containing 3 (NLRP3) inflammasomes." (PMID 34859106, 2021). "Furthermore, we confirmed that the protective effects of TAK-875 were partially independent of GPR40 expression, and TAK-875 improved the hyperlipidemia-induced metabolic inflammatory injury by inhibiting the metabolic inflammatory pathway TLR4 in vivo." (PMID 31934590, 2019). "Oral infection with P. gingivalis significantly increased the expression of Toll-like receptor (TLR) 2 and TLR4 in infected mice compared with sham-infected mice, regardless of whether hyperlipidemia was present." (PMID 21625524, 2011).
Myocardial fibrosis (34 papers, 2012 to 2025). "In vivo experiments revealed the PI3K/AKT/TLR4 signaling pathway causes myocardial fibrosis and weakens erythropoietin inflammation in the rat heart." (PMID 36836952, 2023). "In a study in rats with diabetes, triptolide treatment was shown to induce protection against myocardial fibrosis and the associated impaired left ventricular function by suppressing both the TLR-4 and NF-kB pathways." (PMID 36613560, 2022). "Furthermore, lipid A is able to bind to TLR4, which through different proinflammatory pathways can cause myocardiocyte apoptosis and generate myocardial fibrosis." (PMID 41303145, 2025). "In agreement, previous studies reported that propranolol significantly downregulates B cell lymphoma-2 and BCl-2 associated X protein, which may be related to the TLR4/NF-κB (p65) signal in isoproterenol-induced myocardial fibrosis in mice." (PMID 35893792, 2022). "TLR4 is involved in regulating myocardial fibrosis and hypertrophy by modulating pro-inflammatory factors such as interleukin-6 (IL-6)." (PMID 41300325, 2025). "Studies have shown that cardiac-specific deletion of TLR4 reduces the severity of Ang II-induced myocardial fibrosis." (PMID 41357167, 2025). "Emerging research has consistently shown that Galectin-3 mediates fibrosis, exemplified by inhibiting Galectin-3 that reduces the inflammatory activation of TLR4 and downstream NF-κB to prevent myocardial fibrosis." (PMID 39407295, 2024). "The reduction of LPS in systemic circulation can inhibit TLR4 in cardiac tissue, reduce the translocation of NF-κB to the nucleus, and release inflammatory cytokines, thereby improving cardiac dysfunction and myocardial fibrosis in DCM." (PMID 38472186, 2024). "To further investigate the potential mechanism by which MGIIIE alleviates myocardial fibrosis, we explored the expression of the TLR4-MyD88-NF-κB signaling pathway." (PMID 36594066, 2023). "A recent study suggested that CRP not only is an inflammatory marker, but also promotes inflammation and subsequent myocardial fibrosis through the TLR4/NF-κB/TGF-β pathway." (PMID 36855116, 2023). "MGIIIE plays a role in anti-myocardial fibrosis, by inhibiting TLR4/MyD88/NF-κB signaling expression, and decreasing inflammatory cytokine release." (PMID 36594066, 2023). "A previous investigation proposed that CRP functions not only as an indicator of inflammation but also as a promoter of inflammation, thereby leading to myocardial fibrosis through the TLR4/NF-κB/TGF-β pathway." (PMID 37777746, 2023). "Together, these findings in the present study indicate that LQF alleviated myocardial fibrosis owing to inhibiting TLR4/MyD88/NF-κB signaling pathway and inhibited NLRP3 inflammasome activation." (PMID 35310035, 2022). "The pathogenesis of this myocardial fibrosis involves autoimmune inflammation that is driven in part by TLR4 and its downstream mediator, NF-kB." (PMID 36613560, 2022). "Targeting Toll-like receptor 4 inflammatory pathways and renin-angiotensin system signaling to reduce myocardial fibrosis and abnormal cardiac remodeling following preterm birth warrants further investigation in humans." (PMID 34384550, 2021). "TLR4 activation significantly increased myocardial fibrosis and mRNA expression of myocardial TGF-β and collagen 1α (p < 0.05) as compared to CON group." (PMID 33159115, 2020). "We detected cardiomyocyte apoptosis, ROS stress, myocardial fibrosis, and ventricular expansion and function after TLR4 intervention in EAM mice and observed the mitochondrial morphology changes and mitochondrial dynamic-related protein expression." (PMID 30046376, 2018). "The present study shows that treatment with resveratrol can prevent HMGB1/RAGE/TLR4/NF-κB pathway, oxidative damage, myocardial fibrosis, and inflammation in STZ-induced type 1 diabetic hearts." (PMID 27833703, 2016).
Myocardial fibrosis (continued). "We suggest that aHMGB1 may promote myocardial fibrosis through activation of Toll-like receptor 4 and downstream NFκB signalling, both of which are known to induce pro-fibrotic cytokine expression and myofibroblast activation." (PMID 41291022, 2025). "In summary, BYHWD exerts anti-inflammatory effects by down-regulating the expression of inflammatory factors such as IL-6, IL-1β, IL-18, and NLRP3, and inhibiting the JAK/STAT and TLR4/NF-κB signaling pathways, thereby slowing down the process of myocardial fibrosis." (PMID 40881586, 2025). "TLR4 antagonists prevent myocardial fibrosis by inhibiting the TLR4/MyD88 pathway." (PMID 40098617, 2025). "Previous studies indicated that the MCP-induced Gal-3 inhibition exhibited anti-inflammatory effects in animal models analyzing erectile dysfunction, cerebral-ischemia reperfusion injury, and myocardial fibrosis via the downregulation TLR-4/NF-κB signaling pathway." (PMID 39917614, 2025). "TLR4 activation can increase the infiltration of inflammatory cells in the myocardium, upregulating the expression of inflammatory factors and promoting the production of ROS, which corporately results in cardiomyocyte apoptosis and myocardial fibrosis, and thereby promoting DCM progression." (PMID 30046376, 2018). "We demonstrated that LQF can efficiently inhibit TLR4/MyD88/NF-κB signaling pathway activation and thereby inhibit NLRP3 inflammasome activation and alleviate myocardial fibrosis in MI mice." (PMID 35310035, 2022). "TLR4 activation promoted the transition of EAM to DCM as demonstrated by increased cardiomyocyte apoptosis, myocardial fibrosis, ventricular dilatation, and declined heart function." (PMID 30046376, 2018). "Our results demonstrated that TLR4 activation mainly led to OPA1 dysfunction, which accompanied by increased cardiomyocyte apoptosis, myocardial fibrosis, ventricular dilatation, and declined heart function." (PMID 30046376, 2018). "In conclusion, LQF may downregulate TLR4/MyD88/NF-κB pathway and inhibit the activation of NLRP3 inflammasome, thereby reducing inflammatory response and myocardial fibrosis." (PMID 35310035, 2022). "Blocking TLR2, but not TLR4, activity not only reduced mortality, but also attenuated doxorubicin-induced cardiac dysfunction by 20% and inhibited myocardial fibrosis." (PMID 22808256, 2012). "However, while TLR4 can promote the production of collagen by cells in the heart, the inhibition of TLR4 does not always reduce myocardial fibrosis in cardiac disease models." (PMID 36672353, 2023).
parasite infection (34 papers, 2008 to 2025). "We observed a reduction in TLR4–MyD88 association in infected macrophages indicating some involvement of enhanced sialylation of TLR4 during parasite infection." (PMID 31649671, 2019). "The Tlr4 Asp299Gly and Tlr4 Thr399Ile maternal polymorphisms appeared more frequently in women who had a higher parasitemia and severe anemia, and translated to a significantly increased risk of low birth weight." (PMID 31178840, 2019). "We next compared parasitemia and mortality between different pairs of WT and TLR4-deficient mice (B10 or B6 versus B10/ScN or Tlr4 KO, respectively), after i.p. infection with 2×103T." (PMID 20442858, 2010). "Therefore, decreased Neu1 and increased α2,3-linked sialic acids on TLR4 plays an important role to ascertain successful parasite infection in the host cells." (PMID 31649671, 2019). "Enhanced Neu1-TLR4 and TLR4-MyD88 associations in Neu1-overexpressed cells further intrigued us to explore the role of sialic acids on TLR4 in TLR4-mediated downstream signaling during parasite infection." (PMID 31649671, 2019). "Therefore, the major objective of this study was to examine if B. microti infection cycle in TLR4 deficient C3H/HeJ mice follows the same pattern and assess the impact of parasitemia on the mammalian host pathology and immune response." (PMID 29445365, 2018). "The significantly lower frequency of GTG variants in the T. gondii-infected offspring might suggest a protective role of the mutations in the TLR4 gene against the development of parasitic infection." (PMID 26254559, 2015). "The neutralization of TLR4 in tlr2-/- macrophages completely abolished induction of IFN-β gene expression upon parasite infection, indicating an additive role for both TLRs." (PMID 35154115, 2022). "We, therefore, checked the relevance of Neu1 and siglec-E on TLR4 activation during parasite infection." (PMID 33763070, 2021). "The current study thus demonstrated that differential activation of TLR4-pathways during this parasite infection is under the dual regulation of Neu1 and siglec-E through their action on a common sugar namely sialic acids." (PMID 33763070, 2021). "To specifically pinpoint the effect of Neu1 on TLR4 during parasite infection, we overexpressed Neu1 in macrophage by transfecting a plasmid encoding the Neu1 gene followed by infection with parasite." (PMID 31649671, 2019). "Our observations suggest some close relationship between enhanced sialylation of TLR4 and parasite infection." (PMID 31649671, 2019). "Up-regulation of the miR-27 family is also observed in Apicomplexan parasite infection; miR-27a is induced in ECM and miR-27b is associated with TLR4-mediated epithelial antimicrobial defense and apoptosis." (PMID 27235195, 2016). "Upregulation of the miR-27 family is also observed in the Apicomplexan parasite infection; miR-27a is induced in ECM and miR-27b is associated to the TLR4-mediated epithelial anti-microbial defense and apoptosis." (PMID 26870701, 2016). "Both liver parasite burden and blood parasitemia were compared among WT, TLR2-, TLR4- and MyD88-deficient mice following intravenous P. yoelii sporozoite challenge." (PMID 26667391, 2015). "Strikingly, parasite infection markedly enhanced this phenomenon in two mouse strains (WT and TLR4-/-)." (PMID 25668433, 2015). "Our studies demonstrated that TLR4 signaling is required for optimal production of IFN-γ, TNF-α and nitric oxide (NO) in the spleen of infected animals and, as a consequence, Tlr4−/− mice display higher parasitemia levels." (PMID 20442858, 2010). "We also demonstrated that TLR4 is required for optimal production of inflammatory cytokines and nitric oxide and, consequently, for a better control of parasitemia levels." (PMID 20442858, 2010). "We also evaluated the contribution of TLR4 to the in vivo control of parasitemia levels and survival, as well as to IFN-γ and TNF-α production in the B6 and B10 backgrounds." (PMID 20442858, 2010).
parasite infection (continued). "Parasite infection enhanced TLR4 sialylation and reduced TLR4-NEU1 and TLR4-MyD88 association." (PMID 35479093, 2022). "Some members of the TLR family, such as TLR2 and TLR4, are involved in parasitic infections." (PMID 35927758, 2022). "So, we hypothesized that the hypersialylated TLR4 may be degraded leading to signal termination during this parasitic infection." (PMID 33763070, 2021). "Additionally, the IL-12p40 levels after stimulation with LPS were significantly decreased in both the Trif-/- and Myd88-/- BMDCs compared with the WT BMDCs, which demonstrates the specificity of TLR4 during parasite infection." (PMID 32210480, 2020). "Thus, we have established a possible link between the enhanced TLR4 sialylation mediated by reduced membrane-bound Neu1 during this parasite infection." (PMID 31649671, 2019). "In conclusion, the alternative in the level of expression of TLR2 and TLR4 may imply the role of the innate immune system during parasitic infection." (PMID 27511368, 2016). "In our analysis, TLR4 polymorphisms were associated with susceptibility to a diverse spectrum of infections including Gram-negative, Gram-positive bacteria as well as parasitic infections, such as cutaneous leishmaniasis and neurocysticercosis." (PMID 24282567, 2013). "In accordance, we first reported that C3H/HeJ mice, which express a nonfunctional natural mutant of TLR4, are highly susceptible to infection with T. cruzi, as evidenced by a higher parasitemia and earlier mortality." (PMID 22496959, 2012). "However, the parasite infection increased the F4/80+ cell number in both WT and TLR4-/- groups." (PMID 25668433, 2015). "In accord with this observation, we have previously demonstrated that the lack of expression of functional TLR4 in mice of C3H background caused higher parasitemia and accelerated mortality to T. cruzi infection, although the mechanisms by which this occurs are not yet fully determined." (PMID 20442858, 2010). "In addition, a negative correlation was observed between mRNA expression of TLR4, TLR5, IL-6, and parasitemia levels." (PMID 34336720, 2021). "Maternal TLR4 did not impact the development of MiP when disease severity was evaluated by the levels of peripheral parasitemia and placental parasite burden." (PMID 29440369, 2018). "In fact, TLR4 and TLR9 pathways, other than the TLR2 signal, can promote iNOS/NO production and play an important role in modulating injured livers from BALB/c and C57BL/6 mice during parasitic infection." (PMID 28784165, 2017). "Thus, we observed a good correlation between Neu1-mediated desialylation of TLR4 and activation of the MAPK pathway in addition to NF-κB nuclear translocation indicating higher cellular activation thereby possible inhibition of parasite infection in presence of enhanced Neu1." (PMID 31649671, 2019). "Moreover, this protective effect was not paralleled by a reduction in the level of maternal parasitemia or in the placental parasite burden, suggesting that protection of fetus viability by fetal TLR4 did not rely on antiparasite responses." (PMID 29440369, 2018). "We monitored peripheral parasitemia after infection at G13 in wild-type females and in Tlr4−/− females carrying Tlr4−/− or Tlr4+/− fetuses and found that the Tlr4 genotype in the maternal compartment did not affect the course of parasitemia during pregnancy, irrespective of the fetal Tlr4 genotype." (PMID 29440369, 2018). "The objective of the study was to evaluate and compare serum antibody levels, Leishmania infantum specific IFN-γ production and TLR2 and TLR4 transcripts in non-stimulated blood from dogs with different clinical stages at the time of diagnosis as well as blood parasitemia." (PMID 29547503, 2018).
parasite infection (continued). "In animals injected every other day with AG, following a previously reported protocol, parasitemia kept rising until treatment was stopped on day 13 pi, attaining 3 and 7 fold higher levels of what was usually observed in Tlr4−/− and WT non-treated animals, respectively." (PMID 20442858, 2010). "Additionally, whether the bulky terminal α2,3-linked sialyl residues on TLR4 prevent its association with other adaptor molecules thereby leading to deactivation of TLR4 signaling during this parasite infection has not been established yet." (PMID 31649671, 2019). "Therefore, mice lacking TLR4 expression in a C57BL genetic background are more sensitive than their WT controls to infection with T. cruzi, although these strains do not display the uncontrolled parasitemia and the remarkable earlier mortality previously observed in the TLR4-mutant C3H/HeJ mice." (PMID 20442858, 2010). "We also observed a negative correlation between TLR4, TLR5, TRIF, IL-6, IL-10, and IL-12p35 mRNA expression and parasitemia peak levels in infected mice." (PMID 34336720, 2021). "iRBC- and TLR1/2 and TLR4 agonist-induced CD86 expression was also lower in CD1c+ cells isolated at peak parasitemia than prior to infection, while there was no change in TLR1/2 and TLR4-induced IL-12 expression and all three stimuli, iRBCs, TLR1/2 and TLR4 agonists, increased intracellular TNF." (PMID 31900030, 2020).